EGFR (epidermal growth factor receptor)
Diseases named in the same sentence as EGFR in open-access papers (continued):
Sharing a sentence is not in itself a finding about the gene and the disease.
melanoma (continued). "miR-7 could decrease the expressions of EGFR, IGF-1R and CRAF and further suppressed the activation of MAPK and PI3K/AKT pathways in VemR A375 melanoma cells." (PMID 27448964, 2016). "Finally, we showed a dramatic up regulation of RUNX2 expression with concomitant up-regulation of EGFR, IGF-1R and AXL in melanoma cells resistant to the BRAF V600E inhibitor PLX4720." (PMID 27102439, 2016). "Our studies indicated that miR-7 could decrease the expression of EGFR, IGF-1R and CRAF and partly reverse the resistance to BRAFi in VemR melanoma cells, further suppressed the tumor growth in VemR melanoma xenografted mice model." (PMID 27448964, 2016). "While melanoma is not typically EGFR-driven, expression of miR-7-5p is reduced in metastatic tumors compared to primary melanoma." (PMID 27203220, 2016). "Given that melanoma is typically not driven by aberrant EGFR expression and/or signaling, this study aimed to clarify the functional and clinical relevance of miR-7-5p in melanoma, and to identify critical pathways through which miR-7-5p acts in this disease." (PMID 27203220, 2016). "In addition, we found high levels of phosphorylated EGFR (Y1068) and phosphorylated AXL (Y702) in C8161 melanoma cells, in contrast to C81-61 melanoma cells." (PMID 27102439, 2016). "Introduction of miR-7 mimics could markedly decrease the expressions of EGFR, IGF-1R and CRAF and further suppressed the activation of MAPK and PI3K/AKT pathway in VemR A375 melanoma cells." (PMID 27448964, 2016). "This does not happen in melanoma cells because EGFR is not sufficiently expressed to allow the cell to take advantage of the elimination of this feedback control." (PMID 25885672, 2015). "EGFR, a receptor for AAV6, is expressed by both primary human melanocytes and melanoma cell lines." (PMID 23646140, 2013). "Moreover, HGF was also found to induce resistance to sunitinib, ATE684 (a selective ALK inhibitor), vemurafenib (the BRAF inhibitor, in BRAF-mutant melanoma), and lapatinib (a dual HER2 and EGFR tyrosine kinase inhibitor)." (PMID 23533466, 2013). "First, murine spleen cells derived from SCID mice have been reported to induce ADCC activity against melanoma cells treated with cetuximab, though the effect is not as potent as that by parental mouse monoclonal antibodies against EGFR." (PMID 22922885, 2012). "Elevated levels of the EGF receptor (EGFR) have correlated to poor prognosis in head and neck, ovarian, cervical, bladder and oesophageal cancers but substantial similar data for melanoma is not yet available." (PMID 24281094, 2010). "Also, EGFR and IGF1R are constantly activated in melanoma cells’ resistance." (PMID 40872623, 2025). "Others described melanoma cell sEVs containing various signaling molecules from the MAPK family, HSP70, Tyrp2, and several microRNAs or pro-angiogenic factors (IL-8, VEGF, MMP-2, EGFR) that regulate the proliferation, migration, and invasion capabilities of neighboring cells." (PMID 39596498, 2024). "We therefore propose that identifying expression levels of MITF/SOX10, AXL/EGFR/ERBB3 prior to initiation of treatment may contribute to predicting treatment response to MAPK inhibitors and perhaps advice on drug combination strategies in melanoma." (PMID 36251678, 2023). "Comparable with autocrine EGFR signalling discussed previously, autocrine c-MET/HGF signalling in disseminated cells and CTC clusters is hypothesised to contribute to the survival signalling necessary to evade anoikis during melanoma metastasis." (PMID 37181747, 2023). "However, melanoma cells express little EGFR; therefore, BRAF inhibitors did not stimulate EGFR activation." (PMID 37218919, 2023). "Furthermore, the most potent EGFR inhibitors will be tested for their inhibitory effect against mutant-type EGFR (EGFRT790M), and the most potent anti-BRAF agents will be tested for their anticancer effect against the LOX-IMVI melanoma cell line, which has BRAFV600E kinase overexpression." (PMID 36770936, 2023).
melanoma (continued). "Interestingly, in the early nineties, nuclear EGFR expression has firstly been described in rat hepatocytes (reviewed in:) which is in-line with our finding of nuclear ICOS expression in adjacent hepatocytes from a melanoma liver metastasis." (PMID 37259155, 2023). "In addition, a combination of an EGFR inhibitor and CAP may be a candidate for treating a subset of melanomas, including more aggressive forms." (PMID 37241912, 2023). "While the role for EGFR signalling in anoikis resistance in melanoma cells remains poorly defined, it is hypothesised that the sustained survival signalling provided by autocrine EGF/EGFR activation within clusters of melanoma cells contributes to the survival of disseminated cells." (PMID 37181747, 2023). "The main pathways of enrichment included EGFR tyrosine kinase inhibitor resistance, the MAPK signaling pathway, Ras signaling pathway, FoxO signaling pathway, PI3K-Akt signaling pathway, osteoclast differentiation, IL-17 signaling pathway, proteoglycans in cancer, prostate cancer, and melanoma." (PMID 35496280, 2022). "Notably, miR-7 inhibits the EGFR expression and AKT activity in the melanoma and carcinoma cells." (PMID 35327461, 2022). "Therefore, we hypothesized that RA could down-regulate ADAM17 expression and inhibit EGFR/AKT signaling, thereby affecting the proliferation, migration and chemotherapy sensitivity of melanoma cells." (PMID 34224305, 2021). "Therefore, EGFR does not seem to be a promising target in human and canine melanoma, but targeting of this receptor in the canine disease has not been investigated yet." (PMID 33664868, 2021). "Additionally, FGFR2 promotes melanoma metastasis and recently, the implication of FGFR3 in melanoma growth, metastasis, and EMT behaviors was elucidated, through modulation of phosphorylation levels of ERK, AKT, and EGFR." (PMID 33918490, 2021). "A decrease in the activity of sex determining region Y-box 10 (SOX10) described in some melanomas may lead to signalization through TGF-β, which in turn leads to an increase in the expression of EGFR and the receptor of the platelet-derived growth factor (PDGFRB)." (PMID 32605090, 2020). "Inhibitors of EGFR alone do not have a strong anti-proliferative effect in melanoma cell lines." (PMID 32667922, 2020). "In addition, EGFR was correlated with resistance to BRAF inhibitors by contributing to activity of ERK1/2 and AKT through a physical interaction with urokinase type plasminogen activator receptor (uPAR) in melanoma cells." (PMID 31936151, 2020). "Similarly, HDAC8 expression was increased in malignant melanoma cell models of acquired resistance to BRAF inhibitors due to the deacetylation of the transcription factor CJUN, which promotes the subsequent upregulation of EGFR and ERK signaling." (PMID 32046099, 2020). "The frequency of mutations in the genes is consistent with that reported in the literature for IDH1 and IDH2 in brain tumors, EGFR and KRAS in NSCLCs, KRAS and NRAS in CRCs, BRAF, RAS, PIK3CA, and TERT in thyroid nodules, BRAF, NRAS and cKIT in melanoma, and KRAS in pancreatic pre-operative samples." (PMID 32340363, 2020). "Notably, as with Gal-1 silencing, EGFR impairment did not impact the viability of drug-sensitive parental melanoma cells, which are independent of its kinase activity." (PMID 32784465, 2020). "EGF-dependence was limited to the trametinib-resistant cell line with elevated level of EGFR expression/phosphorylation, and it was conditional as excluding trametinib from the culture medium lacking EGF resulted in the rapid regrowth and reprogramming of melanoma cells." (PMID 31936151, 2020). "Additionally, erlotinib also antagonized LRIG1 knockdown-induced decrease in E-cadherin and increase in vimentin in hypoxia-stimulated melanoma cells, indicating that LRIG1 depression could enhance hypoxia-induced EMT by activating the EGFR/ERK pathway." (PMID 30487162, 2019).
melanoma (continued). "We found that in preclinical models of the long-term vemurafenib-exposed melanoma cells, high EGFR expression could relate to high migratory but not proliferative capacity, vemurafenib and erlotinib resistance, and also elevated PD-L1 expression." (PMID 31514305, 2019). "However, A375‐R melanoma cells only showed a significant increase in the expression of EGFR but not in PDGFRβ levels." (PMID 30582770, 2019). "Now examining, cell-sorted EGFR-positive cells that are able to form colonies in the presence of a BRAFi16, we found that this minor subpopulation corresponds to dedifferentiated states of melanoma (N or U) expressing α- and resistant signatures." (PMID 30429474, 2018). "However, feedback activation of EGFR upon BRAF blockade in BRAFmut CRC cells results in a minimal response to selective BRAF inhibitors with only 5% of patients responding, compared to an 80% response rate in BRAFV600E melanoma patients." (PMID 27999210, 2017). "HER3/ErbB3 is a member of the human epidermal growth factor receptor (EGFR) family and HER3 expression has been correlated with tumor progression and reduction of patient survival in pancreatic, breast, ovarian and gastric cancer, in head and neck squamous cell carcinoma and in melanoma." (PMID 27203743, 2016). "Since EGFR, IGF-1R and CRAF have been known to be the key components of RTK-RAS-RAF-MEK-ERK (MAPK) and/or PI3K/AKT signaling pathways, we further determined if single or combined inhibition of EGFR, IGF-1R and CRAF could suppress the activation of MAPK and PI3K/AKT signaling in VemR melanoma cells." (PMID 27448964, 2016). "We subsequently used small molecular inhibitors of EGFR (gefitinib), IGF-1R (linsitinib), and CRAF (GW5074), as single agent or in combination to further verify whether these genes really participate in BRAFi resistance in VemR A375 melanoma cells." (PMID 27448964, 2016). "Pre- or post-therapy melanoma samples from the other two unresponsive patients (P2 and P5) and from the two responsive ones (P1 and P4), instead, did not have detectable staining of EGFR or AXL." (PMID 25742786, 2015). "In recent studies of thyroid carcinoma and melanoma, SPRY2 and SOX10 have been identified as additional BRAF-EGFR feedback mediators, which suggests that feedback signaling of BRAF V600E to the EGFR might be more complex than initially thought and includes other, hitherto unknown proteins as well." (PMID 26065894, 2015). "Recent studies show that EGFR expression occurs in a significant percentage of BRAF resistant melanomas, and receptor activation, though disadvantageous under normal conditions, becomes beneficial when the MAPK pathway is blocked in BRAFV600E positive melanomas." (PMID 24970815, 2014). "EGFR is not expressed, in general, by melanoma cells, and in vitro studies concluded that EGFR expression is disadvantageous for BRAFV600E melanoma cells in the absence of BRAF or MEK inhibitor drugs, but it confers a selective advantage in the presence of these drugs." (PMID 25344914, 2014). "In vitro treatments with an EGFR inhibitor in combination with a BRAF inhibitor, or monotherapy with dasatinib, appeared to overcome this resistance and could deliver therapeutic efficacy in drug-resistant BRAF-mutant melanoma patients." (PMID 24743024, 2014). "Another potential explanation is that activation of alternative signaling pathways may, in part, explain these results; indeed, the melanoma cell line that lacked an apparent response to MET inhibition, SK-MEL-28, has, for example, an EGFR mutation that may have contributed to this phenomenon." (PMID 37444518, 2023).
melanoma (continued). "Therefore, there are currently no EGFR-targeted therapies approved for human melanomas." (PMID 33664868, 2021). "In addition, as the relationship between EGFR and these miRNAs in human melanoma has not yet been characterized, this suggests a future focus for research that could assist in developing fish-based translational Xmrk models." (PMID 34067095, 2021). "However, activation of EGFR was not necessary to promote signaling via Akt, which suggests that some human melanomas may exhibit different signaling characteristics than in fish models of the disease." (PMID 34067095, 2021). "In melanoma cells resistant to MAPK inhibitors including BRAFi, a state of low expressions of MITF and SOX10 could induce high levels of tyrosine kinase receptors, such as AXL receptor tyrosine kinase (AXL) and epidermal growth factor receptor (EGFR) that help to maintain the resistance." (PMID 32532957, 2020). "Furthermore, by decreasing the expression levels of EGFR, IGF-1R and CRAF, miR-7 could inhibit the activation of RAS/RAF/MEK/ERK (MAPK) and PI3K/AKT pathway and partially reverse the resistance to BRAFi in VemR A375 melanoma cells." (PMID 27448964, 2016). "The striking accuracy of chemotaxis demonstrated by melanoma cells towards serum was more reminiscent of neutrophil chemotaxis towards formyl peptides, or Dictyostelium towards cAMP, which signal through G-protein coupled receptors (GPCRs) rather than growth factor receptors like EGFR and PDGFR." (PMID 25313567, 2014). "As we previously reported, we used melanoma cell line WM983B, in which the endogenous EGFR is not detectable at a protein level, to transiently express EGFR mutants." (PMID 40649937, 2025). "The synergistic impact on cell viability with the addition of a SRC inhibitor to BRAF + EGFR targeting was conserved across BRAFV600E CRC cell lines, but not BRAFV600E melanoma cells." (PMID 36759733, 2023). "In this regard, EGFR, PTEN, ESR1, FGFR2 and ERBB2 were more frequently detected in CSF ctDNA than in blood in a cohort of NSCLC and BC as well as in patients with melanoma and negative CSF cytology." (PMID 34207653, 2021). "The stark difference in the clinical activity of vemurafenib between BRAF mutant melanoma and BRAF mutant CRC was attributed to the complete lack of pathway reactivation in the former, principally related to absent or low level EGFR expression." (PMID 32922659, 2020). "Consistently, our data rule out the involvement of EGFR in mediating ST3GAL1-dependent cell migration and invasiveness and narrow that of NGFR in ST3GAL1-dependent melanoma cell migration." (PMID 33203881, 2020). "This is confirmed by the findings that, melanoma cells grown in MSC-conditioned medium, unlike control cells, do not express a reduction of PDGFR, EGFR and p-ERK after Vemurafenib treatment, well characterised markers of melanoma resistance to Vemurafenib." (PMID 32396749, 2020). "As the BRAF inhibitor vemurafenib is—in contrast to melanoma—not effective in CRC, we combined it with the EGFR inhibitor gefitinib." (PMID 31861874, 2019). "In our work, the EGFR level was not determined, so further investigations are needed to evaluate the validity of ERRFI1 as a prognostic marker in different subtypes of malignant melanoma." (PMID 30641895, 2019). "Consistent with the observed for EGFR, the predicted likelihood and the NRS scores did no correlate (Pearson Correlation Score of 0.03 in melanoma and 0.01 in colorectal)." (PMID 28436422, 2017). "RNA sequencing analysis of DUSP4, EGFR, HER2 and HER3 expression in pan-negative melanomas genotyped through The Cancer Genome Atlas (TCGA) revealed an inverse relationship between DUSP4 and EGFR expression (p-value = 0.03978)." (PMID 26084293, 2015). "We here describe that these features, expression of EGFR, lack of MITF and SOX10, are inherent and occurs independently of drug selection in EGFRHIGH/ERBB3LOW-Invasive melanomas." (PMID 25742786, 2015).
melanoma (continued). "In fact, high expression levels of EGFR are observed in CRC, but not in melanoma cells, explaining the different response of these two tumors." (PMID 26160848, 2015). "The melanoma cell lines WM983A and WM983B used in the present study did not express detectable EGFR and only very low levels of Axl [another partner for EGFR heterodimers], in order to cleanly dissect the specific effects of the inhibitors on the individual mutant EGFR." (PMID 40649937, 2025). "Rapid EGFR feedback activation has been established as one of the mechanisms of intrinsic resistance to BRAFi in BRAFV600E CRC, which does not occur in BRAFV600E melanoma and explains the sensitivity of the latest to BRAF inhibitors in the clinic." (PMID 40481178, 2025). "While our results showed that CD133 activates an EGFR/MAPK pathway in the two melanoma cell lines tested, the activity of MAPK could alternatively be separate and independent of EGFR activation." (PMID 38727313, 2024). "Notably, we observe a significant increase in the basal levels of both EGFR and PD-L1 expression in KRAS G13D A375 melanoma cells but not in NRAS Q61K cells." (PMID 36358868, 2022). "Additionally, we find that while ERBB3 and ERBB2 are affected by the treatment, EGFR was not, further reiterating our previous results that an ERBB3/ERBB2 signaling cascade operates in melanoma and is mostly responsible of the activation of PI3K/AKT signaling." (PMID 28060735, 2017). "Using melanoma cell lines lacking or expressing FLNA, Fiori and collaborators have shown that this protein is an important regulator of EGFR members (including ERBB2) that ensure efficient ligand-mediated activation of these receptors and, consequently, intracellular trafficking and degradation." (PMID 21210970, 2010). "Although our data indicate that Gal-1 and NRP1/EGFR upregulation is a frequent adaptive mechanism in melanoma cells treated with BRAF inhibitors, this signaling cascade may not be critical in every case of melanoma developing drug resistance." (PMID 32784465, 2020). "Mutations were also identified in brain metastases from non-breast primaries in EGFR (3/9 - 33%; two lung and one kidney), HRAS (1/9 - 11%; lung), KRAS (2/9 - 22%; one colon and one lung), NRAS (3/9 - 33%; two lung and one kidney) and PIK3CA (2/9 - 22%; one melanoma and one lung)." (PMID 20604919, 2010).